PIK3CA (phosphatidylinositol-4,5-bisphosphate 3-kinase catalytic subunit alpha)
Diseases named in the same sentence as PIK3CA in open-access papers (continued):
Sharing a sentence is not in itself a finding about the gene and the disease.
breast cancer (continued). "Based on our study, NGS is recommended as follows: 1) for correctly assessing the mutation status of PIK3CA in breast cancer, especially for cases with low tumor content, 2) for the detection of subclonal mutations, and 3) for simultaneous mutation detection in multiple exons." (PMID 26587011, 2015). "In breast cancers, oncogenic mutations in the gene encoding the p110α catalytic subunit (PIK3CA) and deletion or truncation of the gene encoding PTEN are present in up to 45 and 40% of human breast tumours respectively, generally in a mutually exclusive manner." (PMID 26464442, 2015). "In the present study, different types of PIK3CA mutations were analyzed with regard to their frequency, their association with basic characteristics and their prognostic significance in patients with early breast cancer." (PMID 26452060, 2015). "The breast cancer specimen was positive for a heterozygous mutation in PIK3CA (c." (PMID 25671134, 2015). "PIK3CA mutation may contribute to the poor outcome of ER positive breast carcinomas, providing evidence for the combination of PI3K/AKT/mTOR inhibitors and endocrine therapy." (PMID 25816324, 2015). "PIK3CA mutations are one of the most frequent genetic alterations in breast carcinomas." (PMID 26452060, 2015). "In breast cancer patients, a recent study suggests patients with PIK3CA mutations may actually have a more favorable prognosis, and that tumors with PIK3CA mutations irrespective of cancer type might have improved response rates to PI3K-directed therapies." (PMID 24559118, 2014). "The association between PIK3CA mutation and breast cancer prognosis has been controversial." (PMID 24467828, 2014). "Both HER2 and PIK3CA are aberrantly expressed or mutated in many breast cancers." (PMID 25051360, 2014). "Although the relative increase in PIK3CA mutations was modest compared to other genes in breast cancer, this improved sensitivity is vital for affected patients and could lead to positive clinical trial outcomes." (PMID 24970867, 2014). "In addition PIK3CA mutations are the most common genetic aberrations observed in breast cancer and occur most frequently in HER2-amplified and hormone-receptor-positive breast cancers." (PMID 25488803, 2014). "These PIK3CA mutations are predicted to render these breast cancers sensitive to targeted therapy." (PMID 25051360, 2014). "While dysfunction in PI3K pathway can increase tumorogenesis, retrospective data suggest that outcomes might be more favourable in patients with ER+ breast cancer expressing a PIK3CA mutation." (PMID 24670368, 2014). "Given the clinical context of these mutations in breast cancer, these mutations are of potential clinical benefit to the patient that may have implications for PIK3CA inhibitors that target the PI3K/AKT/mTOR pathway." (PMID 24885028, 2014). "Down-regulation of PTEN and oncogenic mutation of PIK3CA compounded with EGFR over expression has been correlated with poor response to trastuzumab treatment as well as a poor clinical outcome in women with HER2+ breast cancer." (PMID 25566499, 2014). "Further evidence of the adverse prognostic effect of PIK3CA mutations in HER2-positive breast cancer was provided in a large randomized Phase III study of patients receiving docetaxel in combination with trastuzumab plus placebo or docetaxel in combination with trastuzumab plus pertuzumab." (PMID 25056500, 2014). "The frequency of PIK3CA mutations in HER2-positive breast cancer has been reported as 22.7% to 39%." (PMID 25542038, 2014). "The PIK3CA gene is mutated in 30-40% of ERalpha+ breast cancers." (PMID 25051360, 2014). "Studies have estimated that between 13 and 31% of HER2+ breast cancers harbor mutations in PIK3CA." (PMID 24252402, 2013). "TMC5 is a transmembrane channel that was overexpressed in PIK3CA-mutated breast cancer." (PMID 23758962, 2013). "Similarly, in the test set, PIK3CA mutation predicted resistance when occurring in a breast cancer cell line." (PMID 23577104, 2013).
breast cancer (continued). "However, one study of 160 Swedish primary breast cancer patients reported an association between PIK3CA mutations and lymph node metastases." (PMID 24083111, 2013). "Hence, high levels of the PIK3CA-GS in estrogen receptor (ER)-positive breast cancer were associated with PIK3CA mutant (genotyped) breast cancers but paradoxically low mTORC1 pathway output." (PMID 23301057, 2013). "In this regard, it is interesting that the JIMT-1 breast cancer cell line, a model of intrinsic resistance to trastuzumab that harbors an activating mutation in the PIK3CA gene and low expression of PTEN, was notably responsive to metformin in vitro and in vivo." (PMID 23986086, 2013). "PIK3CA is also frequently mutated in breast cancer but has an oncogenic role." (PMID 23601657, 2013). "PIK3CA mutation is reported to be observed in 25% to 40% of all breast cancers." (PMID 24245483, 2013). "Several other investigators have also reported that the PIK3CA mutated compared with wild-type genotype is associated with a better prognosis, though a robust prognostic study is yet to be performed in large clinical breast cancer cohorts." (PMID 23301057, 2013). "For these reasons, the response of PIK3CA H1047R-mutated breast cancer xenotumors to the anti-cancer effects elicited by the i.p. administration of metformin might be predictive of more favorable patient outcomes in a clinical setting." (PMID 23986086, 2013). "Moreover, when trastuzumab was combined with metformin to treat PIK3CA-mutated HER2+ breast carcinomas, tumor volume decreased sharply, thus suggesting that metformin is sufficient to overcome in vivo primary resistance to trastuzumab in these tumors." (PMID 23986086, 2013). "The PIK3CA gene is frequently mutated in breast cancers as well as other cancers." (PMID 22970388, 2012). "Mutations in exon 9 and 20 of the PIK3CA gene have been observed in 8% to 40% of breast cancers." (PMID 22935382, 2012). "Here we have assessed the presence of PIK3CA mutations in breast cancer bone metastases." (PMID 22970388, 2012). "It is thought that in breast cancer, oncogenic mutations in PIK3CA or low levels of PTEN expression may confer resistance to treatment with trastuzumab, a monoclonal antibody that targets the HER2/Neu receptor." (PMID 23056620, 2012). "Such early changes suggest that the Pik3ca mutation may be an early event in breast cancer development, a result consistent with findings of PIK3CA mutations in DCIS." (PMID 22666336, 2012). "Moreover, the AKT inhibitor AZD5363 increases the efficacy of lapatinib and/or trastuzumab in xenografts derived from HER2+ breast cancer cell lines harboring PIK3CA mutation." (PMID 22935382, 2012). "This study confirms the high prevalence of PIK3CA mutations in breast cancer." (PMID 22330809, 2012). "Our data suggest that these drugs may be active against breast cancer bone metastases and that the PIK3CA mutation status in bone metastases can be predicted from readily available primary tumor samples." (PMID 22970388, 2012). "However, recent studies suggest that overexpression of AR in breast cancer does occur, and is associated with overexpression of ERα and in breast cancers with PIK3CA mutations in the kinase domain." (PMID 22321971, 2012). "PIK3CA mutations occur frequently in breast cancer bone metastases." (PMID 22970388, 2012). "The prognostic value of PIK3CA mutation status in breast cancer is controversial." (PMID 22330809, 2012). "Then PIK3CA mutation status could serve as a new independent prognostic tool when selecting targeted therapies for patients with ERBB2+ breast cancer." (PMID 22330809, 2012). "Indeed, the PI3K p110 catalytic subunit gene (PIK3CA) is one of the most frequently mutated genes in breast cancer." (PMID 21881167, 2011). "Although the pathological and clinical significance of PIK3CA somatic mutations has been well studied, the contribution of inherited variation in this important oncogene to risk of breast cancer is unknown." (PMID 22033276, 2011).
breast cancer (continued). "PIK3CA mutations occur more frequently in elder patients for HER2-positive breast cancer." (PMID 21676217, 2011). "PIK3CA mutation analysis was performed on tumor biopsies from recurrent disease and in patients with stage 4 breast cancer to determine the prevalence of mutations in advanced disease and to correlate mutation status with the rate of tumor progression and death." (PMID 21362200, 2011). "Indeed, metaplastic breast cancer, a relatively rare form, shows the highest frequency of PIK3CA mutations (47%)." (PMID 21646685, 2011). "Several further studies in breast cancer cells have also shown that the presence of amplified HER2 or the dual presence of PIK3CA mutation and HER2 amplification increases sensitivity to NVP-BEZ235 and GDC-0941, potentially through an increased cell death response." (PMID 21649578, 2011). "A PIK3CA mutation was identified in 16 of the 51 tumors (31.4%; eight in the helical domain, eight in the kinase domain), a prevalence similar to that observed in studies that examined primary breast cancer tissue." (PMID 21362200, 2011). "Here we investigated the influence of germline variation in PIK3CA on breast cancer risk." (PMID 22033276, 2011). "With exception of VANGL2, up-regulation of the genes involved in Wnt signaling pathway, namely WNT5A, MSX2, TCF7L2 and TNFRSF11B, was confirmed in the validation set, further emphasizing the important role of the Wnt signaling pathway in PIK3CA-mutated breast cancer." (PMID 21209903, 2010). "In addition, we have analyzed multiple autopsy samples from six cases that had a primary breast cancer, and found additional EGFR and PIK3CA mutations in breast cancers that metastasized to various sites including the brain." (PMID 20604919, 2010). "We identified HRAS and PIK3CA mutations in the basal breast cancer cell lines SUM 159 and BT20." (PMID 20604919, 2010). "PIK3CA mutations have also been associated with favorable outcome of breast cancer patients." (PMID 21209903, 2010). "Furthermore, amplifications and gain-of-function mutations of PIK3CA have been associated with ovarian cancer, cervical cancer and breast cancer." (PMID 19357772, 2009). "In addition, mutation of PIK3CA correlated with the status of Akt phosphorylation in some breast cancer cells and inhibition of PIK3CA-induced increased apoptosis in breast cancer cells with PIK3CA mutation." (PMID 16168105, 2005). "Therefore, although adding inavolisib to palbociclib and fulvestrant provides additional survival benefits for patients with PIK3CA-mutated advanced breast cancer, its high cost raises concerns regarding its economic value and accessibility across different healthcare systems." (PMID 41496420, 2026). "Since there are multiple drug targets in this pathway, including PIK3CA inhibitors, which are approved for breast cancer, and AKT1 inhibitors, the lower prevalence of mutations in this pathway may lead to worsening disparities in outcomes, as these treatments would not be efficacious in this group." (PMID 41162424, 2025). "Additionally, PIK3CA hotspot mutations may also contribute to therapy resistance in breast cancer, with associations found between these mutations and resistance to chemotherapy (e.g., paclitaxel, anthracyclines) and HER2-targeted therapies like trastuzumab." (PMID 40508087, 2025). "Additionally, the phase II BYLieve study provided evidence that HR‐positive/HER2‐negative advanced breast cancer patients with PIK3CA mutations, who had previously been treated with CDK4/6i, benefited from alpelisib in combination with either aromatase inhibitors (AI) or fulvestrant." (PMID 40206206, 2025). "PIK3CA, a most frequently mutated gene, could activate multiple genetic programs and influence intratumoral heterogeneity which its wild types may have favorable immunotherapy outcomes for patients with breast cancer." (PMID 39872538, 2024).
breast cancer (continued). "A theory could thus be that the patients with ER + /HER2- breast cancers and nodal involvement already in the primary setting may have a greater risk of harboring a PIK3CA mutation and developing resistance to treatment, and could thus be prioritized for mutational testing." (PMID 38822093, 2024). "Thus, controlling the availability of phosphoenolpyruvate and/or fumarate may contribute to treat trastuzumab-resistant breast cancer with PIK3CA mutation." (PMID 38468344, 2024). "This study has shed light upon the differential PIK3CA mutational profiles between relapse and primary tumors, and their associations to clinicopathological variables, especially lymph node status, in a unique paired cohort of patients with confirmed endocrine-resistant breast cancer." (PMID 38822093, 2024). "Therefore, PIK3CA bearing activating mutations could be a driver oncogene in less than half of breast cancers." (PMID 38987766, 2024). "PIK3CA mutations could be detected in up to 50% of ER-positive breast cancer patients." (PMID 38396649, 2024). "NaME-PrO-based enrichment has been applied for enriching PIK3CA hotspot mutations in cfDNA samples from breast cancer (BC) patients." (PMID 36674433, 2023). "Alpelisib may be used more effectively than other drugs in CMT patients when there is a concurrent occurrence of a PIK3CA mutation and a malignant diagnosis, similar to its use to prevent recurrence and metastasis in metastatic human breast cancers with PIK3CA-mutations." (PMID 38033642, 2023). "In light of the clinically meaningful results of the PI3K inhibitors in PIK3CA-mutated metastatic breast cancer (BC) patients, the reliable identification of PIK3CA mutations is of outmost importance." (PMID 37392328, 2023). "Indeed, 58 patients (45.4%) with a PIK3CA mutation had breast cancer." (PMID 36934165, 2023). "In summary, our preclinical data suggest that a bi-steric mTORC1-selective inhibition may be an effective approach for overcoming resistance to standard of care therapeutics in breast cancers, especially in ER+ tumors that harbor mutations that activate mTORC1 including PIK3CA and PTEN." (PMID 37264081, 2023). "It is known that PIK3CA gene mutations, mainly at the level of hotspots in exons 9 (codons 542 and 545) and 20 (codon 1047), confer constitutive oncogenic pathway activation in different types of cancer, including breast cancer, for which it is considered a therapeutic target as well." (PMID 35740668, 2022). "Thus, GDC-0077 may offer exciting opportunities to explore more tolerable and efficacious combinations in melanoma and breast cancer patients harboring PIK3CA mutation." (PMID 35806358, 2022). "Therefore, a putative small molecule inhibitor for USP35 may help overcome resistance to therapy with PI3K α inhibitor for ER+ breast cancer with PIK3CA mutations or hyper-activation of the PI3K pathway in the future." (PMID 34131114, 2021). "Therascreen PIK3CA RGQ PCR kit has also been approved by the FDA as a companion diagnostic for the detection of PIK3CA mutations in plasma samples from patients with advanced-stage breast cancer to determine their eligibility for blocking the PI3Kα mediated pathway." (PMID 33672659, 2021). "However, it has been previously reported that the frequency of PIK3CA mutations may be different in breast cancer patients based on the presence of germline mutations in BRCA1/BRCA2 (in both women and men)." (PMID 34287479, 2021). "Also, 39.1% of breast cancer samples harbored PIK3CA mutations." (PMID 33397889, 2021).
breast cancer (continued). "Indeed, high levels of NRG1β in all HER2+ breast cancer patients were reported to be correlated with higher rates of recurrence, which may be exacerbated by the presence of PIK3CA mutations." (PMID 34344439, 2021). "Thus, BRCA1 and BRCA2 are the most common germline mutated genes, while PIK3CA is the second most common somatic mutated gene in breast cancer patients; however, subtle frequency differences may be related to the age of onset of the disease." (PMID 34287479, 2021). "For PIK3CA mutant subjects, 79.4% were ER+ and this mutation was observed in nearly 40 % of Group 1A patients, indicating that PIK3CA may be an earlier driver for hormone responsive breast cancer during oncogenesis." (PMID 33632156, 2021). "In addition, there is a study that uses alpelisib, a PIK3CA inhibitor, for breast cancer PIK3CA mutated patients, who have shown better survival than that of other treatment, which could be implemented in lung cancer as well." (PMID 34571741, 2021). "Because studies verifying canine PIK3CA H1047R are still limited and the numbers of cases in previous and the present study were relatively low, further large-scale studies are required to determine the frequency and the features of PIK3CA H1047R mutation in canine mammary tumors." (PMID 34359206, 2021). "The PTEN/PIK3CA gene is frequently mutated in spontaneous mammary carcinoma in tree shrews, whereas this phenomenon has not been observed in mouse mammary carcinoma models; thus, tree shrews may be a promising animal model for this type of mammary carcinoma." (PMID 33768009, 2021). "Therefore, treatment-refractory HR+, HER2-, advanced breast cancer patients may undergo F1CDx analysis to determine if they possess a PIK3CA mutation and therefore may benefit from alpelisib treatment." (PMID 32542231, 2020). "Thus, Loibl and coworkers reached the conclusion that PIK3CA mutations are associated with reduced pathological complete response rates in primary HER2-positive breast cancer through the pooled analysis of 967 patients from five prospective trials investigating lapatinib and trastuzumab." (PMID 32210163, 2020). "With the recent FDA approval of alpelisib for the treatment of PIK3CA‐mutated hormone‐receptor positive metastatic breast cancer, tumor molecular profiling to identify somatic mutations and potential molecularly targeted agents is increasingly utilized in the treatment of advanced breast cancer." (PMID 32881420, 2020). "Furthermore, the mutational hotspot of PIK3CA in canine mammary tumors could also be found in human breast cancers, which indicated the importance of PI3K signaling pathway in the development of both human breast cancer and canine mammary tumors." (PMID 33375426, 2020). "Data generated from this study suggests that inhibitors of the PI3K/AKT/mTOR pathway may be a viable strategy for many breast cancer patients, considering 59% of IDCs had measurable levels of PIK3CA mutation, and 26% of IDCs had levels of PIK3CA mutation ≥ 1 × 10−3." (PMID 30813596, 2019). "A study using human breast cancer cell lines and mouse tumor xenografts has shown that activating mutations of PIK3CA and/or decreased expression of PTEN could be responsible of resistance to lapatinib and that this resistance is reversible by double blockade of PI3KCA and mTOR." (PMID 31164152, 2019). "PIK3CA (phosphatidylinositol 3-kinase, catalytic, α-polypeptide), the gene encoding the p110α subunit, are frequently mutated or amplified in the most common human cancers, such as breast cancers, colon cancer, gastric cancer, cervical cancer, prostate cancer, and lung cancer." (PMID 30782187, 2019). "In addition, PIK3CA E453K (TCT > TTT) was associated with an APOBEC signature in breast cancer." (PMID 29748584, 2018). "However, activating mutations in the PIK3CA gene have also been proposed as indicative of a poor outcome for Trastuzumab-based therapies in human epidermal growth factor receptor 2 (HER2) positive breast cancer models." (PMID 29523855, 2018).